MIR429 (microRNA 429)
Synonyms: hsa-mir-429; MIRN429; mir-429
Gene: MicroRNA gene on chromosome 1 (1,169,005 to 1,169,087, forward strand). Ensembl gene ENSG00000198976.
Diseases named in the same sentence as MIR429 in open-access papers:
MIR429 is named in the same sentence as 3 diseases in open-access papers, as found by Europe PMC text mining. Sharing a sentence is not in itself a finding about the gene and the disease. The quoted sentences say what the papers report.
glioma (1 paper, 2020). A benign or malignant brain and spinal cord tumor that arises from glial cells (astrocytes, oligodendrocytes, ependymal cells). "The cancer genes MIR200A, MIR200B, and MIR429 in the different aberrant chromosomal region 1p36.33-p36.32 between tumor tissue (no aberration) and cell subpopulations (gain) have been described as implicated in regulation of tumor cell proliferation in glioma." (PMID 32634135, 2020).
cancer (2 papers, 2020). A tumor composed of atypical neoplastic, often pleomorphic cells that invade other tissues. "GRHL2 upregulates expression of the MIR141, MIR200A, MIR200B, MIR200C and MIR429 microRNAs by binding to their regulatory elements in a number of cancers." (PMID 32005677, 2020).
MIR429 also shares sentences with these, for which no sentence is quoted: tumor (1 paper).